BCL2A1 (BCL2 related protein A1)
Description:
Retards apoptosis induced by IL-3 deprivation. May function in the response of hemopoietic cells to external signals and in maintaining endothelial survival during infection (By similarity). Can inhibit apoptosis induced by serum starvation in the mammary epithelial cell line HC11 (By similarity).
Synonyms: BCL2L5; BFL1; GRS; HBPA1; ACC-1; ACC-2; ACC2; ACC1
Tractability: Small molecule: a drug acting on it is in phase 2 or 3 trials; a structure with a bound ligand is known; a high-quality ligand is known; it belongs to a druggable protein family. PROTAC: a small molecule that binds it is known.
Target class: Ion channel; Other ion channel; Bcl-2 family; Miscellaneous ion channel
Chemical probes: ML041, ML042
Gene: Protein-coding gene on chromosome 15 (79,960,892 to 79,971,196, reverse strand). Ensembl gene ENSG00000140379.
Subcellular location: Cytoplasm
Pathways (Reactome):
Developmental Biology: Regulation of MITF-M-dependent genes involved in apoptosis
Disease: Nuclear events stimulated by ALK signaling in cancer
Gene Ontology:
Molecular function: protein binding; channel activity
Biological process: extrinsic apoptotic signaling pathway in absence of ligand; intrinsic apoptotic signaling pathway in response to DNA damage; mitochondrial fusion; negative regulation of apoptotic process; positive regulation of apoptotic process; release of cytochrome c from mitochondria; regulation of apoptotic process; transmembrane transport
Cellular component: cytoplasm; cytosol; mitochondrial outer membrane
Genetic constraint (gnomAD): Loss-of-function variants: 12 observed, 17.77 expected, observed/expected ratio (o/e) 0.68, 90% interval 0.43 to 1.09. The upper end of that interval is the gene's LOEUF score, 1.09, which puts it in group 4 of 6, group 1 being the genes least tolerant of losing a copy. Missense variants: 158 observed, 214.93 expected, observed/expected ratio (o/e) 0.74, 90% interval 0.64 to 0.84. Synonymous variants: 71 observed, 80.91 expected, observed/expected ratio (o/e) 0.88, 90% interval 0.72 to 1.07.
Homologues: Orthologues: macaque BCL2A1 (97% identical), chimpanzee BCL2A1 (94% identical), pig BCL2A1 (86% identical), dog BCL2A1 (77% identical), rat Bcl2a1 (77% identical), mouse Bcl2a1d (71% identical), mouse Bcl2a1a (71% identical), mouse Bcl2a1b (71% identical), guinea pig BCL2A1 (70% identical), mouse Bcl2a1c (42% identical), Caenorhabditis elegans ced-9 (15% identical). Paralogues in human: BCL2 (24% identical), BCL2L1 (23% identical), BAX (22% identical), MCL1 (22% identical), BAK1 (21% identical), BOK (18% identical), BCL2L2 (18% identical), BCL2L10 (17% identical).
Diseases named in the same sentence as BCL2A1 in open-access papers:
BCL2A1 is named in the same sentence as 104 diseases in open-access papers, as found by Europe PMC text mining. Sharing a sentence is not in itself a finding about the gene and the disease. The quoted sentences say what the papers report.
melanoma (39 papers, 2008 to 2025). A malignant, usually aggressive tumor composed of atypical, neoplastic melanocytes. "BCL2A1 has also been associated with resistance to chemotherapy in breast cancer, melanoma and colon cancer." (PMID 37889551, 2023). "BCL2A1 expression is associated with more dismal clinical responses to BRAF inhibitors in melanoma patients." (PMID 34063141, 2021). "Together, these data indicate that splicing modulator E7107 inhibits BCL2A1 expression through intron-retention-associated NMD in melanoma cells." (PMID 30635584, 2019). "In melanoma, BCL2A1 is implicated in resistance to BRAF inhibitors further supporting its pro-survival activity." (PMID 26460486, 2015). "These regulatory phenomena have important consequences in melanoma treatment, where either TRIM28 overexpression or TRIM17 knockout lowers BCL2A1 protein levels and restores melanoma cell susceptibility to B-Raf protooncogene and serine/threonine kinase (BRAF)-directed therapy." (PMID 38225560, 2024). "Furthermore, BCL2A1 expression was associated with metastatic disease in melanoma and hepatocellular carcinoma." (PMID 26556430, 2014). "Previously, Haq and colleagues demonstrated that BCL2A1 is a melanoma-specific oncogene and likely plays a key role in the development of resistance to BRAF inhibitors." (PMID 41465443, 2025). "BCL2A1 (B-cell lymphoma 2-related protein A1) is an anti-apoptotic member of the BCL-2 family and is associated with the resistance of melanoma cells to BRAF-targeted therapy." (PMID 39100077, 2024). "TRIM17 augments BRAF-targeted therapy sensitivity of melanoma cells by preventing BCL2A1 from being ubiquitinated and degraded by TRIM28." (PMID 35832194, 2022). "Gene expression profiling of 40 metastatic and 42 primary melanoma patient samples found that BCL2A1 was overexpressed in metastatic samples." (PMID 35900226, 2022). "For example, TRIM17 binds to BCL2A1 and prevents TRIM28-mediated ubiquitination and degradation of BCL2A1 in melanoma cells." (PMID 33966039, 2021). "This inhibitory effect results in the stabilization of BCL2A1 and increased resistance of melanoma cells towards apoptosis." (PMID 34069831, 2021). "In agreement, we have previously demonstrated substantial upregulation of BCL2A1 expression in MITFhigh melanoma cells." (PMID 32466509, 2020). "We first attempted to elucidate the splicing-relevant mechanism for BCL2A1 reduction in melanoma cells." (PMID 30635584, 2019). "In general, melanoma cell lines, which all express relatively high level of BCL2A1, were extremely sensitive to E7107 treatment as measured by Emax." (PMID 30635584, 2019). "Convincingly, BCL2A1 cDNA expression significantly compromised the cytotoxic effect of E7107 to cytostasis in both melanoma cell lines." (PMID 30635584, 2019). "The patientswith normal karyotype showed a higher frequency of BCL2A1 inabnormal karyotype and cancer cell lines demonstratedhematopoietic malignancies and melanoma." (PMID 31285648, 2019). "BCL2A1 has been recently described as an oncogene responsible for resistance to BRAF inhibition in melanoma." (PMID 28599664, 2017). "Amplification of the family member, BCL2A1 in 30% of melanoma, was shown to contribute to resistance to BRAF inhibition." (PMID 24743024, 2014). "A member of this family, BCL2A1, was shown to be amplified in 30% of melanoma and contribute to resistance to BRAF inhibition (see section “Intrinsic Resistance to BRAF and MEK Inhibitors”)." (PMID 24743024, 2014). "However, in melanoma, TRIM28 upregulates the sensitivity of melanoma cells to targeted BRAF therapy by promoting the degradation of BCL2A1." (PMID 39100077, 2024). "Indeed, Desagher team showed that TRIM17 inhibits TRIM28-mediated ubiquitination and degradation of BCL2A1, thereby promoting the survival of BCL2A1-dependent cells, including chemotherapy-resistant melanoma cells." (PMID 35883457, 2022).
melanoma (continued). "Similarly, a study of spontaneous melanoma central nervous system metastasis in preclinical models showed that BCL2A1 was significantly up-regulated in melanoma cell lines, and the overexpression of BCL2A1 facilitated intracranial tumour growth." (PMID 35900226, 2022). "Similarly, BCL2A1 is highly upregulated in several hematopoietic malignancies and melanoma, in which it contributes to chemoresistance." (PMID 34069831, 2021). "In aggregate, the data indicate that splicing inhibition of BCL2A1 may trigger BCL2A1-dependent cytotoxicity, suggesting a potential therapeutic strategy for melanoma with high BCL2A1 expression." (PMID 30635584, 2019). "Consequently, E7107 selectively induces apoptosis in BCL2A1-dependent melanoma cells and MCL1-dependent NSCLC cells." (PMID 30635584, 2019). "Consequently, E7107 induces preferential cytotoxicity in BCL2A1-high/dependent melanoma cells and MCL1-high/dependent NSCLC cells." (PMID 30635584, 2019). "More recently, human BCL2A1 mRNA was found to be overexpressed in various solid tumors such as stomach, colon cancer, and breast cancer, skin squamous cell carcinoma, hepatocellular carcinoma and melanoma." (PMID 23441221, 2013). "Moreover, it has been reported that BCL2A1 is a key pro-survival factor in melanoma cells." (PMID 30635584, 2019). "Suppression of BCL2A1 might have clinical benefit in this group of melanomas." (PMID 24743024, 2014). "The correlation between BCL2A1 amplification, directly regulated via the oncogene MITF, and poor BRAF inhibitor sensitivity was found both in melanoma cell lines and patient samples." (PMID 35900226, 2022). "Collagen stiffness induced the expression of melanoma differentiation genes TRPM1, PMEL, TYR and MLANA, as well as well as the proliferation and survival genes CDK2 and BCL2A1." (PMID 36135194, 2022). "More interestingly, KO of TRIM17 restored sensitivity to PLX4720 in resistant melanoma cells, by relieving the inhibition of TRIM28-mediated ubiquitination of BCL2A1 and thereby by reducing BCL2A1 level." (PMID 34069831, 2021). "Cotreatment of melanomas with BRAF inhibitors and obatoclax, an inhibitor BCL2 family member, overcomes resistance to BRAF inhibitors in BCL2A1-amplified cells." (PMID 34063141, 2021). "The antiapoptotic BCL2 family member BCL2A1, a transcriptional target of MITF, is amplified in about one-third of melanomas." (PMID 34063141, 2021). "At the transcriptional level, MITF controls genes involved in cell survival (BCL2, HIF1A, BCL2A1), migration (DIAPH1, MET) and proliferation (CDK2, TBX2, CDKN1B), providing important signals for growth of melanoma cells." (PMID 34289891, 2021). "BCL2A1, a lineage-specific anti-apoptotic protein in the BCL2 family, is amplified and overexpressed in MITF-high melanomas, and confers resistance to BRAF inhibitor." (PMID 24743024, 2014). "Interestingly, Bcl2A1 was much lower than the canonical Bcl2, which was the opposite of the case in BCG-vaccinated melanoma patients." (PMID 40699791, 2025). "Nevertheless, despite the upregulation of BCL2A1 and BIRC3 observed in our experiment, the majority of melanoma cells died, suggesting that RGD-apoptins may be able to bypass the defense mechanisms of these tumor cells." (PMID 41465443, 2025). "This would suggest that splicing modulators, by inducing BCL2A1 intron retention and subsequent NMD, may impinge on the BCL2A1 dependency to induce cell death in melanoma cells." (PMID 30635584, 2019). "Therefore, overexpression of TRIM28 or downregulation of TRIM17 reduce the protein level of BCL2A1 and restore sensitivity to B-Raf proto-oncogene, serine/threonine kinase (BRAF)-targeted therapy in melanoma cells that exhibit a survival dependency on BCL2A1." (PMID 30974870, 2019). "BCL2A1 has been identified as an oncogene in melanoma and B-cell malignancies;21 however, there are no reports on a role for BCL2A1 in breast cancer cells." (PMID 29760958, 2018).
melanoma (continued). "BCL2A1 expression is apparently restricted to melanocytic lineage as it is indirectly controlled by MITF, and because of this its expression is limited to high-MITF-expressing melanomas." (PMID 24743024, 2014). "We did not choose BCL2A1, although its basal expression was highly upregulated in DMBC21 compared with DMBC11 cells, as BCL2A1 is also a target of microphthalmia-associated transcription factor (MITF), which is a melanoma-specific protein." (PMID 32466509, 2020). "Additionally, we have chosen not to focus on BCL2A1, a recently described melanoma oncogene and mediator of BRAF inhibitor resistance in a subset of melanomas, as this was the subject of an independent analysis in our program." (PMID 24983357, 2014).
breast carcinoma (20 papers, 2013 to 2025). "In particular, we analyzed other TCGA datasets and the International Cancer Genome Consortium (see GitHub repository associated with the publication for more details) and we only found these mutations of BCL2A1 associated with breast cancer samples." (PMID 31825969, 2019). "Another study, comparing expression levels between stages of breast cancer, found an association with a worse survival of the patient and high expression levels of BCL2A1." (PMID 31825969, 2019). "Here, we applied a high-throughput computational mutational scan to predict the effects of missense mutations found in breast cancer samples, on both the structural stability of Bcl2a1, and the binding between Bcl2a1 and BH3-only proteins." (PMID 31825969, 2019). "In this regard, the upregulation of BCL2A1 in breast cancers is associated with a significant decrease in relapse-free survival." (PMID 29760958, 2018). "Interestingly, in advanced breast cancer a higher expression of BCL2A1 mRNA was found when compared to less advanced tumours, suggesting an association of BCL2A1 expression with later and more severe disease stages." (PMID 26556430, 2014). "Previous studies have shown that BCL2A1 is closely related to the tumorigenesis and resistance to chemotherapy of multiple solid tumors, such as breast cancer." (PMID 37889551, 2023). "BCL2A1 expression plays an important role in cell survival after CHCP treatment in breast cancer cells and is potentially regulated by TNF-alpha." (PMID 35260587, 2022). "The increase of BCL2A1 activity is known to lead to suppression of apoptosis and appears to impact on cell survival and resistance to treatment in breast cancer." (PMID 34289891, 2021). "However, dependencies on other pro-survival BCL-2 family members may exist depending on the type of cancer and treatment used, as recently reported data on breast cancer showed a positive correlation between not only MCL-1 but also BCL-2A1 expression and an inverse association with BCL-2 expression." (PMID 32913197, 2020). "A study, where different solid tumor tissues were compared, found the highest expression of BCL2A1 in breast cancers." (PMID 31825969, 2019). "We found a marked signature for the pro-survival BCL2A1 gene, which is up-regulated in breast cancer and its subtypes." (PMID 31825969, 2019). "The deep mutational scanning allowed us to provide a more comprehensive view, beyond mere changes in expression levels, of the alterations of Bcl2a1 in breast cancer." (PMID 31825969, 2019). "We find two complexes between the up-regulated Bcl2A1 and two down-regulated BH3-only candidates (i.e., Hrk and Nr4a1) as targets associated with reduced apoptosis in breast cancer samples for future experimental validation." (PMID 31825969, 2019). "Since brain metastasis typically occurs in the late stage of breast cancers, elevated BCL2A1 expression in MDA-MB-231BR is a reasonable observation, although the details need to be elucidated." (PMID 27723829, 2016). "As predicted from an earlier report, both BCL2A1 gene and proteins were expressed only marginally in other human breast cancer cell lines, such as MCF-7 and T-47D, a human mammary epithelial cell line MCF-10A, and a human glioblastoma cell line U87MG." (PMID 27723829, 2016). "Amongst a panel of different solid tumour tissues, the highest expression of BCL2A1 mRNA was detected in breast cancer samples." (PMID 26556430, 2014). "Moreover, MCPIP1 expression has been shown to act as a potent tumor suppressor in breast cancer cells by inducing tumor apoptosis through selectively suppressing the expression of antiapoptotic gene transcripts, including Bcl2L1 and Bcl2A1." (PMID 39815326, 2025). "RT-PCR analysis of 30 breast cancer samples revealed that the expression of BCL2A1 was increased in advanced breast cancer compared to early cancers, suggesting that BFL-1 may serve as a contributory factor in cancer progression." (PMID 35900226, 2022).
breast carcinoma (continued). "Moreover, in vitro follow-up studies will consider differential gene regulation as a mechanism of survival since we recently discovered BCL2A1 to be a key gene for CHCP resistance in breast cancers." (PMID 35807413, 2022). "Unraveling to what extent putative BH3-like interactors are deregulated in breast cancer and clarifying their possible interaction with Bcl2a1 at the structural level, might provide a valuable source of information." (PMID 31825969, 2019). "The Bcl2a1 mutations in breast cancer are not predicted to locally change the binding affinity with the BH3 only proteins used in our study." (PMID 31825969, 2019). "Our results suggest that the interaction between Bcl2a1 and Hrk could be of interest to explore in breast cancer since their deregulation points in the direction of evading apoptosis, a cancer hallmark." (PMID 31825969, 2019). "Four mutations were reported for Bcl2a1 (M75R, L99R, Y120C and, V145L), whereas we did not identify missense mutations altering Hrk in the breast cancer samples under investigation." (PMID 31825969, 2019). "An earlier report demonstrated that BCL2A1 was more highly expressed in advanced breast cancers compared to less-advanced cancers in clinical situations, implying that BCL2A1 expression could be a poor prognostic factor." (PMID 27723829, 2016). "Nr4a1 might also be an interesting BH3-candidate for Bcl2a1 in breast cancer for similar reasons." (PMID 31825969, 2019). "The induction of antiapoptotic genes, including B-cell CLL/lymphoma 2 (BCL2), BCL2 related protein A1 (BCL2A1), BCL2 like 1 (BCL2L1), BCL2L2, and myeloid cell leukemia 1 (MCL1), has been observed in multiple cancers, including breast cancer." (PMID 36853387, 2023). "To assess the potential involvement of MUC1-C in the regulation of BCL2A1, we established MDA-MB-468 breast cancer cells stably expressing tetracycline-inducible control shRNA (tet-CshRNA) or MUC1 shRNA (tet-MUC1shRNA)." (PMID 29760958, 2018). "We addressed this objective by assessing in the DS-exposed luminal breast cancer cells the expression of key regulators of these processes, including B-cell lymphoma-2 (BCL-2)-related protein A1(BCL-2A1), cellular FLICE-inhibitory protein (cFLIP), Beclin1, and heme oxygenase-1 (HO-1)." (PMID 41148796, 2025). "The five antiapoptotic genes (BCL2, BCL2A1, BCL2L1, BCL2L2, and MCL1) are frequently overexpressed in ER-positive breast cancer cells, and these genes have been used as clinical biomarkers in the diagnosis of breast cancer." (PMID 36853387, 2023). "Here, we revealed that BCL2, BCL2A1, BCL2L2, and MCL1 but not BCL2L1 were overexpressed in estrogen receptor (ER)-positive breast cancer cells and clinical biopsies." (PMID 36853387, 2023).
leukemia (15 papers, 2002 to 2026). A malignant (clonal) hematologic disorder, involving hematopoietic stem cells and characterized by the presence of primitive or atypical myeloid or lymphoid cells in the bone marrow and the blood. "For example, in a mouse model of MYC-driven leukemia, BCL2A1 can cooperate with MYC to accelerate leukemogenesis." (PMID 38205232, 2024). "This leukemia was characterized by insertion of the vector provirus into the BCL2A1 gene, with resultant BCL2A1 over-expression." (PMID 23118966, 2012). "For example, Meike and his team found that proper regulation of BCL2A1 and BCL-XL could improve the resistance of leukemia cells to therapeutic agents." (PMID 36338998, 2022). "Gene expression data suggests that BCL2A1 is not expressed at high levels in all leukemia cells." (PMID 32582592, 2020). "To address whether BCL2A1 over-expression can promote development of leukemia/lymphoma, in the absence of a specific cooperating oncogene such as MYC, we used a murine bone marrow transplantation model." (PMID 23118966, 2012). "Finally, BFL1 (BCL2A1) inhibition may also be an interesting option since the recent discovery of specific inhibitors, but the drug has not been specifically tested in leukemia models." (PMID 37065864, 2023).